HIF1A (hypoxia inducible factor 1 subunit alpha)
Diseases named in the same sentence as HIF1A in open-access papers (continued):
Sharing a sentence is not in itself a finding about the gene and the disease.
tumor (continued). "Lactate-HIF-1α signaling in TAMs is crucial for promoting vascularization of the tumor: while TAMs only constitute 1–6% of the cellularity of the tumor, they were found in one study to express more vascular endothelial growth factor (VEGF) mRNA than the rest of the tumor combined." (PMID 39796781, 2025). "Furthermore, the potential involvement of these targets in key processes such as hypoxia, metabolism, and tumor progression through HIF-1α signaling further supports the therapeutic potential of RG6016 in tumor biology." (PMID 40428124, 2025). "Based on the IPA of differentially expressed genes, we discovered activity changes of several pathways significantly associated with tumor behavior were activated over the course of surgery (FDR <5%), including IL-6, IL-8, HMGB1, HIF1α, IL-1, TGFβ, and TNFα signaling." (PMID 40331601, 2025). "Since overexpression of VEGF and its upstream regulator HIF-1α plays a critical role in driving tumor angiogenesis, which provides essential nutrients for LC growth, we assessed MVD and the expression levels of HIF-1α and VEGF at lesion sites using immunohistochemistry (IHC)." (PMID 41210868, 2025). "Moreover, hypoxia is a common feature of the tumor microenvironment, with hypoxia-inducible factors (HIFs), particularly HIF-1α, playing a key role in the adaptive response to low oxygen levels, promoting angiogenesis and metastasis." (PMID 41316451, 2025). "However, these confines can be altered with the induction and stabilization of HIF1α and the initiation of angiogenesis, leading to tumor growth well beyond their original limitations." (PMID 40806669, 2025). "In addition to its involvement in tumor progression, HIF-1α significantly impacts female reproductive health." (PMID 40136686, 2025). "They hypothesized that with the increasing level of HIF1α altering the microenvironment of the tumor and surrounding area, the epigenetic makeup of the tumor was able to mutate." (PMID 40806669, 2025). "Notably, the embedded U87-MG spheroids displayed characteristics of GBM, such as hypoxia and HIF-1α expression, which are crucial for understanding tumor progression and chemoresistance." (PMID 40277699, 2025). "Hypoxia, a hallmark of solid tumors driven by inadequate vascularization relative to rapid tumor growth, activates HIFs, mainly HIF-1α, which orchestrate transcriptional programs that regulate angiogenesis, metabolic adaptation, immune modulation, and ECM remodeling." (PMID 40869364, 2025). "For example, under hypoxic conditions, the activation of HIF-1α may lead tumor cells to readjust their metabolic pathways, thereby resisting therapies targeting HIF-1α." (PMID 39980550, 2025). "Based on our findings, we propose that HIF-1α may potentiate anti-tumor immune responses through its regulatory role in promoting CD4+ Tcon proliferation and activation." (PMID 41230345, 2025). "However, it has been suggested that HIF-1α modulates tumor cell survival by blocking the pro-apoptotic axis, a reduction in tumor size being related to HIF-1α overexpression." (PMID 40227577, 2025). "The current findings support such a view with bevacizumab targeting HIF-1α to reduce the progression of tumor development, while anlotinib reinforces these actions and may also protect the body against drug resistance." (PMID 41041327, 2025). "Whether inhibition of HIF‐1α and angiogenesis would lead to prominent anti‐tumour effects on OSCC are interesting to be investigated." (PMID 39757131, 2025). "Furthermore, HIF-1α exerts tumor-suppressive effects under normoxic conditions, notably through the inhibition of mTOR signaling via the upregulation of DDIT4." (PMID 39470609, 2025). "Recent data have shown that HIF-1α may increase the expression of genes related to tumor neoangiogenesis, cancer cell proliferation, and metastasis." (PMID 40227577, 2025).
tumor (continued). "Although a high ratio and related gene signatures associate with poor outcomes, only tumour stage and select gene expressions like TP53I11 are independently predictive, indicating that the WWOX/HIF1A axis functions within a broader context of subtype-specific risk factors." (PMID 41007296, 2025). "PD-L1 expression is also closely linked to glycolysis, HIF-1a and GLUT1 expression, hence a responding tumour with less glycolytic activity may potentially result in PD-L1 downregulation." (PMID 40188291, 2025). "HIF-1α regulates critical pathways, including the expression of vascular endothelial growth factor and immune checkpoint upregulation, leading to tumor-infiltrating lymphocyte dysfunction and recruitment of immunosuppressive cells like regulatory T cells and myeloid-derived suppressor cells." (PMID 39981236, 2025). "Furthermore, aberrant expression of HIF-1α not only promotes PD-L1 expression but also suppresses the function of tumor-infiltrating lymphocytes (TILs), ultimately activating tumor immune evasion." (PMID 40936898, 2025). "Recent multi-omics studies have shed light on how HIF-1α may exert tumor suppressive effects, particularly by examining the early transcriptional response to acute hypoxia and identifying specific target genes regulated by HIF-1α." (PMID 39470609, 2025). "For assessment of the tumor microenvironment, HIF1α levels were also evaluated in tumor spheroids." (PMID 40151834, 2025). "Interestingly, the activated HIF1α shows a reduction of tumor mass and volume in breast cancer cells." (PMID 40444035, 2025). "The following section therefore reviews available clinical evidence, bridging mechanistic insights from bench to bedside, and evaluating whether HIF-1α stabilization by Roxadustat indeed correlates with tumor progression in cancer patients." (PMID 41311849, 2025). "The upregulation of HIF-1α during tumor development can enhance the Warburg effect." (PMID 40032849, 2025). "Similarly, elevated levels of hypoxia inducible factor 1-α (HIF1-α) contributes to both a hypoxic tumor microenvironment and chemo resistance." (PMID 40332549, 2025). "Antrodia camphorata also suppresses HIF-1α expression and helps to reduce tumor hypoxia adaptation." (PMID 40508113, 2025). "Thus, Myc not only promotes metabolic changes via HIF1a stabilization but also establishes an immune-suppressive tumor microenvironment by enhancing M2 macrophage polarization and directly impairing CD8 T cell function." (PMID 40330466, 2025). "A recent study reported that HIF-1α can upregulate programmed death-ligand 1, a protein that helps tumors evade immune detection by suppressing T-cell activity, thereby promoting immune evasion and contributing to tumor progression in ESCC." (PMID 40746896, 2025). "Any involvement of PI3K/AKT/HIF-1α signaling in the synergistic anti-tumor effects of anlotinib and bevacizumab may expose new therapeutic targets and biomarkers." (PMID 41041327, 2025). "Oxygen deficiency activates HIF-1α (hypoxia-inducible factor 1-alpha), which induces VEGF expression, supporting angiogenesis, and activates EMT-related genes such as SNAIL and TWIST, which increase tumor cell invasiveness." (PMID 40362280, 2025). "Unsurprisingly, hypoxia (0.5% O2) induced HIF-1α expression in all three tumour cell models." (PMID 40176088, 2025). "Exploring the underlying mechanisms, lactylation modification may contribute to tumor progression by activating oncogenic signaling pathways, such as HIF-1α and MYC." (PMID 41458606, 2025). "This may result from the hypoxic microenvironment in the lower lobes, which promotes glycolysis by upregulating LDH-A expression via hypoxia-inducible factor-1α (HIF-1α), accelerating tumor growth." (PMID 41142602, 2025). "However, despite the importance of the transcription factor HIF-1α, our data showed low expression in tumor tissues obtained from the TCGA, as well as a null effect on overall survival." (PMID 40072116, 2025).
tumor (continued). "Although PX‐478 and BPR0C261 can suppress the tumour vascularity, it remains unclear if they both suppress HIF‐1α‐mediated angiogenic pathway." (PMID 39757131, 2025). "Importantly, RUNX2′s ability to stabilize HIF-1α and amplify angiogenesis in normoxic regions highlights its role in reshaping the bone niche to favour tumour colonization." (PMID 40806771, 2025). "FGL1 plays a regulatory role in tumor glycolysis through the PI3K/AKT/HIF-1α pathway." (PMID 41024301, 2025). "Moreover, the ESCC pathological tumor–node–metastasis stage, T classification, lymph node metastasis, and differentiation can be evaluated via HIF-1α expressions." (PMID 40002862, 2025). "However, there was an observed reduction in tumor development in the PRCC‐TFE3 KI/Hif1α KO group and PRCC‐TFE3 KI/Hif1α/Hif2α DKO group." (PMID 39807625, 2025). "LOX enhances the hypoxia adaptation of tumour cells by upregulating HIF‐1α, which in turn activates the NF‐κB pathway and drives the secretion of inflammatory factors (e.g., IL‐6, TNF‐α), further recruiting immunosuppressive cells (e.g., TAMs, MDSCs) to form a pro‐cancer TME." (PMID 40179101, 2025). "In addition, an acidic, lactate-rich environment directly induces apoptosis and dysfunction in effector T cells and, via hypoxia-inducible factor 1α (HIF-1α), upregulates PD-L1 on tumor cells, further impairing CD8+ T-cell activity." (PMID 40672941, 2025). "Second, deeper molecular investigations are required to elucidate the specific regulatory mechanisms of G6PD on HIF-1α, alongside comprehensive spatial single-cell analyses and in vivo lineage tracing to resolve spatial heterogeneity in G6PD-HIF-1α interactions within tumor microenvironments." (PMID 41050691, 2025). "HIF‐1α is regarded as a key indicator of tumor neovascularization." (PMID 40515512, 2025). "The findings of the study suggest that high HIF-1α expression may be an indicator of tumor radio-resistance and can be considered as a biomarker to guide the determination of postoperative RT strategies." (PMID 40512281, 2025). "Circadian rhythm disruption‐mediated HIF‐1α overexpression drives tumor progression." (PMID 40772466, 2025). "Moreover, tumour progression necessitates cellular adaptation to low-oxygen conditions, a process mainly driven by hypoxia-inducible factor-1α (HIF-1α), which orchestrates the expression of hypoxia-responsive genes." (PMID 40806771, 2025). "Notably, methylation‐defective HIF‐1α knock‐in mice exhibit increased tumor growth and angiogenesis." (PMID 40227962, 2025). "HIF-1α inhibition may be considered a promising therapeutic strategy to prevent cytotoxicity resistance and improve survival by affecting tumor de-differentiation, angiogenesis, and autophagy." (PMID 40512281, 2025). "However, hypoxia also upregulates hypoxia-inducible factor-1α (HIF-1α), which can foster tumor recurrence or metastasis." (PMID 40612869, 2025). "Thus, this study employed a combination of amide proton transfer weighted imaging (APTw), DWI, IVIM, and diffusion kurtosis imaging (DKI) to examine the expression of EC HIF-1α in relation to tumor metabolism and blood perfusion." (PMID 40444079, 2025). "Additionally, HDAC inhibitors can suppress tumor angiogenesis and the expression of the HIF-1α protein." (PMID 40032849, 2025). "Hydroxylation stabilizes HIF-1α under hypoxia, promoting tumor adaptation and survival." (PMID 40427595, 2025). "HIF1α activation drives adaptive responses, including enhanced angiogenesis, increased invasiveness, chemotherapy resistance, and immune evasion, collectively promoting tumor recurrence." (PMID 41467954, 2025). "Moreover, we analyzed the functions and potential pathways of crucial genes related to CLDN12 expression, including HSPA8 and HIF-1α, in the process of tumor progression." (PMID 41461671, 2025). "Consequently, tumor cell-free extracts were prepared and subsequently injected into shrimp to evaluate changes in HIF-1α expression." (PMID 40441532, 2025).
tumor (continued). "HIF-1α is known to be a master regulator of tumorigenesis, altering the transcription of many genes involved in cell proliferation and bringing about the metabolic adaptations that characterize tumor cells." (PMID 41041327, 2025). "More directly, a research team inhibited the expression of HIF-1α and found that the tumor-killing factors secreted by NK cells were increased after the inhibition, which also illustrates the double-sided role of hypoxia in the anti-tumor effects of NK cells." (PMID 40696413, 2025). "HIF1A, a classical hypoxia-inducible factor subunit, induces the expression of matrix metalloproteinases and promotes the degradation of the extracellular matrix, thereby increasing the invasion and metastasis of tumour cells." (PMID 40624675, 2025). "HIF-1α can inhibit the pharmacological effects of dendritic vaccines in a 4T1 breast cancer model, suggesting that hypoxia may inhibit the anti-tumor effects of DCs to act as a tumor-promoting agent." (PMID 40696413, 2025). "Interestingly, these proteins were also expressed in healthy tissue, highlighting the critical roles of the tumor microenvironment and HIF1A status in regulating their expression." (PMID 40332447, 2025). "Additionally, IH activates hypoxia‐inducible factor HIF‐1α, which modifies m6A methylation, altering tumor cell gene expression and enhancing their growth and immune evasion." (PMID 40916616, 2025). "This section explores the mechanisms through which HIF-1α impacts immunotherapy, focusing on its role in immune checkpoint regulation, modulation of tumor-infiltrating immune cells, resistance to immunotherapy, and potential therapeutic strategies targeting HIF-1α." (PMID 39981236, 2025). "HIF-1α is considered a common transcription factor for hypoxic cells in the tumor microenvironment, activating transcription of downstream genes including (Vascular Endothelial Growth Factor) VEGF to provide oxygen and nutrients for PLGC cells, participating in PLGC occurrence." (PMID 40458722, 2025). "The tumor obtained from Myr-NE treated xenografts also showed substantial attenuation of Ki67 compared to Myricetin treatment group, confirming the effective downregulation of HIF-1α in TNBC xenografts." (PMID 40552278, 2025). "EVs (tumor-derived biomarkers), HIF-1α (hypoxia and angiogenesis biomarkers), and serum amyloid A (acute-phase reactants) are the foremost key biomarkers in CAS, which are involved in coagulation, inflammation, angiogenesis, vascular remodeling, and oxidative stress." (PMID 39857281, 2025). "Consistent with our hypothesis, co-treatment with DFO and HIF1A knockdown significantly enhanced the proliferation and migration abilities of tumor cells." (PMID 41198650, 2025). "To further verify these hypotheses, we attempted an in vivo study using a Hep3B xenograft model to assess the tumor-suppressive effect of the combination treatment with HIF-1α inhibition and a ketogenic diet (KetoCal®)." (PMID 41465202, 2025). "The higher the HIF-1α levels in the tissue sample, the greater the size of the tumor." (PMID 40429943, 2025). "Furthermore, ROS accelerate HIF-1α-dependent angiogenesis, as tumor metastasis requires adequate blood supply, and ROS-activated HIF-1α promotes new blood vessel formation, thus providing pathways for distant tumor cell metastasis." (PMID 40563367, 2025). "Several HIF-1α target genes that we had previously identified in the mouse ccRCC model were upregulated in ccRCC cells, confirming that the tumour cells display the characteristic HIF-α-mediated gene expression signature of mouse and human ccRCC." (PMID 40473819, 2025). "HIF1α is a well- established prognostic marker for predicting tumor response to treatment." (PMID 41426972, 2025). "Reduces HIF‐1α expression, enhances DSBs and tumour cell death." (PMID 41028942, 2025). "However, upon “awakening,” increasing tumor mass exacerbates hypoxia, which stabilizes HIF-1α by inhibiting its proteasomal degradation." (PMID 41210868, 2025).
tumor (continued). "For example, previous studies indicate that RPLP2 deficiency leads to stress-induced autophagy of gynecological tumors, and RPLP2 could facilitate HCC tumor growth by regulating glycolysis through the activation of the PI3K/AKT/HIF-1α pathway." (PMID 40564039, 2025). "Moreover, it was reported that overexpression of HIF-1α in NB leads to activation of sonic hedgehog (SHH) signaling which subsequently increases tumor angiogenesis, migration, and invasiveness." (PMID 40032892, 2025). "The suppression of tumor cell master regulator HIF-1α was involved in the drug effects." (PMID 41041327, 2025). "Moreover, Rgcc32 is known to be upregulated by HIF-1α, promoting adaptive responses that facilitate tumor growth and survival under hypoxic conditions." (PMID 40806360, 2025). "MRI revealed that the tumor volume of the HIF1α-or HIF2α-knockout mice was significantly (p < 0.01) lower than that of the empty vector group, but the tumor volume of the dual HIF1α and HIF2α-knockout group was significantly (p < 0.01) greater than that of the empty vector group." (PMID 40370575, 2025). "In tumor-like, lactate-rich hypoxic environments, the stabilization of lactylated HIF-1α may potentiate glycolytic and prosurvival gene programs (e.g., VEGF and GLUT1), thereby enhancing metabolic adaptation, cell survival, and chemoresistance." (PMID 40760493, 2025). "Therefore, blocking HIF-1α signaling in NK cells has been shown to improve their anti-tumor efficacy." (PMID 41511303, 2025). "Tumor hypoxia, mediated by hypoxia-inducible factor 1-alpha (HIF-1α), promotes resistance." (PMID 41007699, 2025). "In addition, some studies have shown a high correlation between HIF-1α expression and advanced cancer, and it was observed that the higher the HIF-1α expression is, the higher the tumor stage is." (PMID 40430040, 2025). "One study observed elevated expression of KDM5C and HIF-1α at GBM tumor margins." (PMID 40450300, 2025). "Notably, simultaneous interference with TFE3 in P4+TFE3+ CAF and HIF1A in tumor cells more effectively inhibited xenograft tumor growth compared to single‐gene interference." (PMID 40917018, 2025). "Importantly, HIF-1α depletion eliminated FABP7 induction in tumor-conditioned macrophages, confirming its upstream regulatory role." (PMID 40765822, 2025). "Importantly, ONECUT3 promotes tumor growth in a glycolysis-dependent manner through hypoxia-inducible factor 1α (HIF-1α)." (PMID 40032849, 2025). "Lactate acts as a signal metabolite, modulating gene expression through inhibition of histone deacetylases (HDACs), affecting the tumor epigenome, and may contribute to the stabilization of HIF-1α, enhancing hypoxia-like responses in some tumor contexts." (PMID 41008923, 2025). "Furthermore, metformin inhibits hypoxia-inducible factor 1-alpha (HIF-1α), a transcription factor promoting angiogenesis and glycolysis under low oxygen conditions, thus hindering tumor growth." (PMID 40283503, 2025). "HIFs, particularly HIF-1α, promote tumor cell survival, inflammation, and immune escape." (PMID 41383608, 2025). "Our study corroborated this positive correlation, suggesting that combined evaluation of PD-L1 and HIF-1α expression could provide valuable insights into tumor biology and treatment strategies." (PMID 39996842, 2025). "Furthermore, studies have demonstrated that ROS generated during trauma‐induced injury and tumor progression play a crucial role in stabilizing HIF‐1α responses, highlighting their importance in immune reprogramming." (PMID 40587842, 2025). "Upon activation in hypoxic settings, HIF-1α initiates a transcriptional program that facilitates invasion, angiogenesis, metabolic reprogramming, and cell survival, collectively contributing to tumor growth and metastasis." (PMID 41311849, 2025). "Indirectly, this connection could influence the expression of CAIX, as the CAIX gene is under the transcriptional control of the Akt/HIF-1α axis, which is frequently activated in tumour cells." (PMID 41375254, 2025).